ENSG00000273734 (novel protein, readthrough between OAZ1 and SPPL2B)
Gene: Protein-coding gene on chromosome 19 (2,269,525 to 2,341,172, forward strand). Ensembl gene ENSG00000273734.
Genetic constraint (gnomAD): Missense variants: 215 observed, 174.25 expected, observed/expected ratio (o/e) 1.23, 90% interval 1.1 to 1.38. Synonymous variants: 92 observed, 68.81 expected, observed/expected ratio (o/e) 1.34, 90% interval 1.13 to 1.59.